MARS2 (methionyl-tRNA synthetase 2, mitochondrial)
Synonyms: MtMetRS; SPAX3; COXPD25; MetRS
Tractability: PROTAC: its protein half-life has been measured; a small molecule that binds it is known.
Target class: Enzyme; Ligase
Gene: Protein-coding gene on chromosome 2 (197,705,369 to 197,708,395, forward strand). Ensembl gene ENSG00000247626.
Subcellular location: Mitochondrion matrix
Pathways (Reactome):
Metabolism of proteins: Mitochondrial tRNA aminoacylation
Gene Ontology:
Molecular function: methionine-tRNA ligase activity; aminoacyl-tRNA ligase activity; ATP binding; nucleotide binding
Biological process: methionyl-tRNA aminoacylation; tRNA aminoacylation for protein translation
Cellular component: mitochondrial matrix; mitochondrion
Genetic constraint (gnomAD): Loss-of-function variants: 33 observed, 46.36 expected, observed/expected ratio (o/e) 0.71, 90% interval 0.54 to 0.95. The upper end of that interval is the gene's LOEUF score, 0.95, which puts it in group 4 of 6, group 1 being the genes least tolerant of losing a copy. Missense variants: 720 observed, 808.89 expected, observed/expected ratio (o/e) 0.89, 90% interval 0.84 to 0.95. Synonymous variants: 351 observed, 348.94 expected, observed/expected ratio (o/e) 1.01, 90% interval 0.92 to 1.1.
Gene-disease validity (ClinGen):
ClinGen rates the evidence that MARS2 causes each of these diseases.
mitochondrial disease (autosomal recessive): Definitive.
Homologues: Orthologues: chimpanzee MARS2 (99% identical), macaque MARS2 (97% identical), pig MARS2 (90% identical), rabbit MARS2 (89% identical), dog MARS2 (87% identical), rat Mars2 (87% identical), mouse Mars2 (86% identical), guinea pig MARS2 (82% identical), zebrafish mars2 (56% identical), tropical clawed frog mars2 (49% identical), Drosophila melanogaster MetRS-m (42% identical). Paralogues in human: MARS1 (24% identical), VARS2 (19% identical), VARS1 (18% identical), IARS2 (16% identical), IARS1 (16% identical), LARS2 (15% identical), LARS1 (14% identical).
Diseases named in the same sentence as MARS2 in open-access papers:
MARS2 is named in the same sentence as 37 diseases in open-access papers, as found by Europe PMC text mining. Sharing a sentence is not in itself a finding about the gene and the disease. The quoted sentences say what the papers report.
Autosomal recessive spastic ataxia with leukoencephalopathy (7 papers, 2012 to 2023). "Rearrangements in MARS2 gene were shown to cause neurodegeneration in autosomal recessive Spastic Ataxia with leukoencephalopathy (ARSAL)." (PMID 33276480, 2020). "With the aid of this knowledge, we identified MARS2 to be mutated in Autosomal Recessive Spastic Ataxia with Leukoencephalopathy (ARSAL) patients." (PMID 22448145, 2012). "MARS2 mutations were shown to cause autosomal recessive spastic ataxia with leukoencephalopathy (ARSAL), which is also a type of neurodegeneration disorder." (PMID 36641423, 2023). "Remarkably, these findings led to the discovery that mutations in the orthologous human gene, MARS2, are responsible for the neurodegenerative disease Autosomal Recessive Spastic Ataxia with Leukoencephalopathy (ARSAL)." (PMID 26761199, 2015). "We further show that rearrangements in its human homologue, MARS2 (Methionyl Aminoacyl-tRNA Synthetase 2, NP_612404.1), are responsible for a human neurodegenerative disease named ARSAL, for Autosomal Recessive Spastic Ataxia with Leukoencephalopathy, or Spastic Ataxia type 3 (SPAX3, OMIM #611390)." (PMID 22448145, 2012).
Leukoencephalopathy (5 papers, 2013 to 2023). This term describes abnormality of the white matter of the cerebrum resulting from damage to the myelin sheaths of nerve cells. "Mutations of MARS2 have been linked to spastic ataxia, as well as neurodevelopmental delay, and white matter abnormalities (leukoencephalopathy), cortical and cerebellar atrophy, as well as corpus callosum thinning." (PMID 33875891, 2021).
spastic ataxia (3 papers, 2013 to 2022). "In this study, there was no causative mutation associated with spastic ataxia, such as SACS/VAMP1/KIF1C/MARS2/MTPAP/AFG3L2(AR), detected." (PMID 35572931, 2022).
breast carcinoma (2 papers, 2022 to 2023).
cervical cancer (1 paper, 2023). A primary or metastatic malignant neoplasm involving the cervix. "We also observed overexpression of MARS2 in human pancreatic, breast and cervical cancer cells." (PMID 36774778, 2023).
developmental delay (1 paper, 2026). "Furthermore, we show that impaired mars-2 activity leads to reduced mitochondrial-encoded protein abundance, depletion of mitochondrial membrane potential, fragmented mitochondrial morphology, and mild developmental delay, although the animals remain viable." (PMID 41359510, 2026).
hyperhomocysteinemia (1 paper, 2020). A serious metabolic condition caused by mutations in the MTHFR gene, medications, or nutritional deficiency. "MARS2 gene duplication has been associated with increased ROS, and the promotion of oxidative stress has long been observed in hyperhomocysteinemia." (PMID 32003121, 2020). "Based on the hypothesis that MARSs sense and generate homocysteine signals and promote hyperhomocysteinemia‐associated disease onset, we collected blood samples from clinically confirmed cases of NTDs and CHDs and carried out copy number variation (CNV) analysis for MARS and MARS2‐encoding genes." (PMID 32003121, 2020).
leukemia (1 paper, 2018). A malignant (clonal) hematologic disorder, involving hematopoietic stem cells and characterized by the presence of primitive or atypical myeloid or lymphoid cells in the bone marrow and the blood. "The similar latency and features of the disease in MAR and MARS2 mice suggests that the principal effect of SphK2 loss was on leukemia initiation rather than rate of disease progression." (PMID 29441205, 2018). "Notably there were fewer deaths resulting from ALL in MARS2 animals with only 43% of deaths being due to ALL, resulting in a significant increase in leukemia free survival in MARS2 mice (p = 0.044)." (PMID 29441205, 2018).
lung carcinoma (1 paper, 2023). "Overexpression of MARS2 in lung cancer cells would indicate that MARS2 is associated with human lung cancer." (PMID 36774778, 2023). "We observed significant elevation of cellular TIGAR levels by MARS2 knockdown in A549 and H460 lung cancer cells." (PMID 36774778, 2023). "To assess the possible correlation of MARS2 and cancer, we compared the MARS2 expression levels of 4 normal lung cells (IMR90, MRC-5, primary small airway epithelial cells, and WI-38) and 12 lung cancer cell lines (A549, Calu-1, Calu-3, ChaGo-k1, EKVX, HOP92, H322, H322M, H460, H520, H522, H1299)." (PMID 36774778, 2023).
neural tube defect (1 paper, 2020). A congenital defect characterized by failure of the neural tube to close completely; this results in the presence of openings in the brain or spinal cord. "Increased copy numbers of MARS or MARS2‐encoding genes were more frequently detected in patients of neural tube defects (NTDs) and congenital heart defects (CHDs)." (PMID 32003121, 2020).
non-small cell lung carcinoma (1 paper, 2023). A group of at least three distinct histological types of lung cancer, including non-small cell squamous cell carcinoma, adenocarcinoma, and large cell carcinoma.
cancer (1 paper, 2023). A tumor composed of atypical neoplastic, often pleomorphic cells that invade other tissues. "This would indicate that MARS2 is associated with only with cancer metastasis." (PMID 36774778, 2023). "Therefore, we tried to investigate the effect of MARS2 knockdown on other representative characteristics of cancer progression in A549 cells." (PMID 36774778, 2023). "Furthermore, we also performed gene expression analysis comparing MARS2 expression between cancer and normal samples across various cancers through OncoDB." (PMID 36774778, 2023). "The results also indicated overexpression of MARS2 in cancer cells." (PMID 36774778, 2023). "Under the assumption that MARS2 is associated with EMT, we hypothesized that cancer cell migration and invasion would be suppressed when the expression of MARS2 is downregulated." (PMID 36774778, 2023).
metabolic disease (1 paper, 2021). A congenital disorder (due to inherited enzyme abnormality) or acquired (due to failure of a metabolically important organ) disorder resulting from an abnormal metabolic process. "The disorders known to be associated with the affected genes range from embryonic lethality (e.g., MRPL55 and LIG3) and metabolic diseases (e.g. acyl-CoA synthetase long chain family member 5 (ACSL5)) to neurodevelopmental disorders (e.g., methionyl-tRNA synthetase 2 (MARS2))." (PMID 34915862, 2021).
MARS2 also shares sentences with these, for which no sentence is quoted: Leigh syndrome (2 papers); neurodegenerative disease (2); Sepsis (2); spastic ataxia 3 (2); acute stress disorder (1); Alpers Disease (1); Alpers syndrome (1); Ataxia (1); autoimmune polyendocrinopathy (1); autosomal recessive spastic ataxia (1); epilepsy (1); Lethal Infantile Mitochondrial Disease (1); leukodystrophies (1); mitochondrial disease (1); Mitochondrial encephalopathy (1); neuroblastoma (1); Neurodevelopmental delay (1); neurodevelopmental disorder (1); ovarian failure (1); Parkinson disease (1); sensorineural hearing loss with (1); skin disorder (1); tumor (1); viral infection (1).